CD151 (CD151 molecule (Raph blood group))
Diseases named in the same sentence as CD151 in open-access papers (continued):
Sharing a sentence is not in itself a finding about the gene and the disease.
osteosarcoma (continued). "To investigate the metabolic vulnerability of cancer cells regulated by CD151, we conducted an untargeted metabolomic analysis in osteosarcoma cells using liquid chromatography coupled with mass spectrometry (LC/MS) analysis." (PMID 36209197, 2022). "Collectively, these data establish that CD151 is a key mediator of sphingolipid metabolism and provide a new approach to developing novel CD151-based targeted therapies for osteosarcoma." (PMID 36209197, 2022). "Our previous study demonstrated that CD151 positively correlates with lung metastasis and predicts poor prognosis in human osteosarcoma and that CD151 promotes osteosarcoma cell migration, invasion, and metastasis in vitro and in vivo." (PMID 36209197, 2022). "Our previously published study has shown that CD151 promotes osteosarcoma cell metastasis in vitro and in vivo." (PMID 36209197, 2022). "Here, we performed integrated transcriptomic and metabolomic analyses of osteosarcoma and identified sphingolipid metabolism as the top CD151-regulated pathway." (PMID 36209197, 2022). "A knockdown of CD151 inhibits osteosarcoma lung metastasis in vivo via the GSK-3/-catenin/MMP9 pathway." (PMID 36077137, 2022). "CD151 expression in osteosarcoma cells with high metastatic potential was significantly higher than in those with low metastatic potential (p<0.001)." (PMID 27556355, 2016). "CD151, a tetraspanin family protein involved in cell-cell and cell-extracellular matrix interaction, is differentially expressed in osteosarcoma cell membranes." (PMID 27556355, 2016). "This study aimed to confirm the positive relationship between osteosarcoma metastasis and CD151 expression, and to examine the role of CD151 on osteosarcoma cell migration and invasion." (PMID 27556355, 2016). "Taken together, CD151 induced osteosarcoma metastasis likely by regulating cell function through adhesion signaling." (PMID 27556355, 2016). "To investigate the biological function of CD151 in osteosarcoma, we next evaluated the viability, cell cycle progression, and apoptotic rates of the various ΔCD151 LM8 and MG63.2 cells." (PMID 27556355, 2016). "This study presents clinical and experimental evidence of the role of CD151 in osteosarcoma metastasis." (PMID 27556355, 2016). "Consistent with the putative role of CD151 in human osteosarcoma metastasis, we observed that CD151 expression in osteosarcoma cells with high metastatic potential was significantly higher than that in cells with low metastatic potential." (PMID 27556355, 2016). "CD151 expression was also silenced with shRNA in osteosarcoma cells of high metastatic potential, and cell adhesion, migration and invasion were evaluated in vitro and pulmonary metastasis was investigated in vivo." (PMID 27556355, 2016). "In contrast, CD151 immunoreactivity was detected in a wide range of intensities in osteosarcoma tissue samples." (PMID 27556355, 2016). "Both osteosarcoma cell lines were transduced with sh-CD151-expressing lentiviral vectors (KD1 and KD2) or with the empty lentiviral vector (vector control)." (PMID 27556355, 2016). "LM8 and MG63.2 osteosarcoma cell adhesion following CD151 knockdown was significantly reduced compared with vector control cells (p<0.001)." (PMID 27556355, 2016). "We have previously shown that CD151 was highly expressed on the membrane of MG-63 osteosarcoma cells as compared to human hFOB1.19 osteoblastic cells." (PMID 27556355, 2016). "Taken together, our results demonstrate that CD151 knockdown attenuates osteosarcoma tumor pulmonary metastasis and points to a new role for CD151 as a regulator of cell adhesion between tumor cells and the extracellular matrix." (PMID 27556355, 2016). "One protein--CD151 located in net nodes was verified to be over-expressed in osteosarcoma tissue by immunohistochemistry." (PMID 20470422, 2010). "To confirm whether CD151 regulates sphingolipid content, we loaded osteosarcoma cells with green fluorescent dye-labeled ceramide or sphingomyelin." (PMID 36209197, 2022).
osteosarcoma (continued). "Future studies are required to explore whether these signaling pathways in osteosarcoma cells regulate c-myc expression in response to CD151 challenge." (PMID 36209197, 2022). "Notably, CD151-overexpression in preclinical patient-derived osteosarcoma tumors were more vulnerable to the sphingolipid synthesis inhibitor, myriocin." (PMID 36209197, 2022). "Depletion of CD151 significantly shortened the half-life of endogenous c-myc in osteosarcoma cells." (PMID 36209197, 2022). "Next, we investigated whether CD151 mediates sphingolipid metabolism by SPTLC1 in osteosarcoma cells." (PMID 36209197, 2022). "To examine whether CD151 promotes c-myc stabilization in osteosarcoma cells, we measured the half-life of c-myc in the presence and absence of CD151 using a cycloheximide chase assay." (PMID 36209197, 2022). "Importantly, inhibiting the CD151/sphingolipid metabolism pathway would greatly inhibit osteosarcoma tumorigenicity, and CD151 expression is a potentially useful biomarker for predicting the efficacy of sphingolipid metabolism inhibition." (PMID 36209197, 2022). "The overexpression of CD151 is further confirmed by immunohistochemistry in osteosarcoma tissues." (PMID 36077137, 2022). "CD151 was shown to be highly expressed in osteosarcoma cell metastasis." (PMID 36077137, 2022). "CD151 regulates sphingolipid metabolism primarily through SPTCL1 in osteosarcoma." (PMID 36209197, 2022). "The c-myc mRNA and protein levels were examined in osteosarcoma to investigate whether CD151 activates endogenous c-myc." (PMID 36209197, 2022). "Taken together, CD151 promotes the migration, invasion, and metastasis of osteosarcoma by altering adhesion, suggesting that it may prove to be a critical diagnostic and/or prognostic marker as well as therapeutic target." (PMID 27556355, 2016). "Hence, CD151 most likely affects the later stages of osteosarcoma progression, in which cells invade into surrounding tissue and encounter the extracellular matrix." (PMID 27556355, 2016). "In addition, the adhesion of the osteosarcoma cells to the extracellular matrix was compromised upon CD151 silencing." (PMID 27556355, 2016). "In order to test its role in osteosarcoma, we next studied whether CD151 silencing reduced the cell-cell attachment or cell adhesion of osteosarcoma cells." (PMID 27556355, 2016). "Furthermore, cell-cell attachment and adhesion in osteosarcoma cells were markedly decreased with CD151 knockdown as was the phosphorylation of p38 and Akt and the expression levels of FAK and integrinβ1." (PMID 27556355, 2016). "We next investigated whether CD151 ablation attenuated pulmonary metastasis in vivo using an orthotopic osteosarcoma tibial model with pulmonary metastasis model." (PMID 27556355, 2016). "In addition, CD151 expression was silenced in osteosarcoma cells with high metastatic potential (ΔCD151 cells), and the adhesion, migration and invasion of these cells were subsequently evaluated." (PMID 27556355, 2016). "CD151 may be a key molecule in regulating the tumorigenesis and migration of osteosarcoma due to its membrane protein function." (PMID 20470422, 2010). "Furthermore, osteosarcoma patients with elevated CD151 expression have poor overall survival." (PMID 36077137, 2022). "Furthermore, our previous work has suggested that CD151 may represent a new biomarker in the detection and diagnosis of human osteosarcoma." (PMID 27556355, 2016). "Because elevated adhesion to neighboring cells and extracellular matrix may increase cellular migration and subsequently influence the invasion of malignant cells, the reduced metastasis observed with ablation of CD151 may be mediated through suppression of osteosarcoma cell adhesion." (PMID 27556355, 2016). "Thus, this study aimed to investigate the role of CD151 in osteosarcoma metastasis." (PMID 27556355, 2016).
osteosarcoma (continued). "Data mining from the osteosarcoma GEO database (GSE42352, n = 127) was used to explore the CD151-related pathways and biological functions." (PMID 36209197, 2022). "The results showed that CD151 and SPTLC1 expression levels were highly correlated in osteosarcoma samples." (PMID 36209197, 2022). "Having established that CD151 reprograms sphingolipid metabolism primarily through SPTCL1, we further explored the possibility of developing new osteosarcoma treatments." (PMID 36209197, 2022). "We also examined the correlation between CD151 and SPTCL1 mRNA expression in a cohort of osteosarcoma GEO databases (GSE42352, n = 127)." (PMID 36209197, 2022). "CD151 is known to support adhesion strengthening, which is consistent with the present study in which ablation of CD151 inhibited the stable cell-cell attachments in LM8 and MG63.2 osteosarcoma cells." (PMID 27556355, 2016). "In addition, we found the upregulation of CD151 in the proteomic data, which is a known activator of GSK3B and positive regulator of β‐catenin expression, promoting osteosarcoma metastasis." (PMID 36520032, 2023). "It was speculated that CD151 might interact with c-myc pathways and regulate sphingolipid metabolism key enzyme SPTLC1 expression in osteosarcoma cells." (PMID 36209197, 2022). "We observed that CD151 positively regulated c-myc protein expression in osteosarcoma cell lines without altering the mRNA level of c-myc, suggesting that the regulation of c-myc by CD151 occurs at the post-transcriptional level." (PMID 36209197, 2022). "Furthermore, CD151 silencing suppressed osteosarcoma metastasis without altering osteosarcoma cell viability or proliferation in vitro as well as LM8 or MG63.2 tumor morphology and growth in vivo." (PMID 27556355, 2016). "Thus, suppression of CD151 expression did not affect osteosarcoma cell viability, cell cycle progression or apoptosis." (PMID 27556355, 2016). "However, no research about CD151 in OS was reported and this was the first report about its over-expression in osteosarcoma cell line and sample, and can enlarge the knowledge of CD151 in cancer." (PMID 20470422, 2010).
liver cancer (8 papers, 2013 to 2025). An epithelial or non-epithelial malignant neoplasm that arises from the liver. "Its association with CD151 suggests a role in promoting migrasome formation, contributing to liver cancer invasiveness and angiogenesis." (PMID 40909272, 2025). "Our findings demonstrate significantly elevated protein expression levels of CD151 and CD31 genes in HCC tissues compared to adjacent normal tissues, indicating a higher CD151 expression in liver cancer tissues associated with increased vascularization." (PMID 38840183, 2024). "We demonstrate that CD151 is linked to migrasome formation, affecting the invasive capabilities of liver cancer cells." (PMID 38840183, 2024). "CD151, another member of the tetraspanin family, is linked to highly invasive cancer cells, and its overexpression correlates with poor prognoses in various cancers, including lung cancer, colorectal cancer, prostate cancer, and liver cancer." (PMID 38840183, 2024). "Previous investigations have affirmed the influence of CD151 on migrasome generation; however, the precise ramifications of CD151 on migrasome dynamics and its implications for the invasiveness of liver cancer cells remain elusive." (PMID 38840183, 2024). "TSPAN4, identified as a marker for migrasomes, emerged as a potential player in liver cancer metastasis due to its significant correlation with CD151." (PMID 38840183, 2024). "Previous research underscores CD151’s role in enhancing migration and invasion in liver cancer cells." (PMID 38840183, 2024). "In summary, our findings suggest that CD151 expression mirrors migrasome localization and is significantly positively correlated with liver cancer angiogenesis and distant metastasis." (PMID 38840183, 2024). "Our investigation reveals a correlation between high CD151 expression and migrasome activity in liver cancer, indicating their involvement in angiogenesis and distant metastasis." (PMID 38840183, 2024). "As subcutaneous tumors developed, liver cancer cells expressing CD151 normally (Mock group) exhibited substantial angiogenesis, characterized by thick and tortuous blood vessels." (PMID 38840183, 2024). "A correlation analysis revealed a notable association between “CD151 & TSPAN4” across all datasets (Correlation coefficient | r |>0.4), indicating their heightened correlation in liver cancer." (PMID 38840183, 2024). "Our investigation posits the pivotal involvement of migrasomes in the vascular remodeling process within liver cancer particularly through the expression of CD151 and its correlation with migrasome activity and angiogenesis observed in our animal models." (PMID 38840183, 2024). "To discern the relationship between CD151 and migrasomes, we constructed CD151-SiRNA and conducted RNAi KD experiments on liver cancer cells (HCCLM3 and MHCC97H)." (PMID 38840183, 2024). "These experiments collectively suggest that CD151 expression in liver cancer cells plays a crucial role in migrasome generation, with CD151 acting as a label within these organelles." (PMID 38840183, 2024). "This study unveils the significant influence of CD151 through migrasome on the vascular metastasis of cancer cells in liver cancer, providing crucial insights for further understanding the functions of migrasome and liver cancer through vascular metastasis." (PMID 38840183, 2024). "In summary, our findings support the notion that elevated CD151 expression promotes migrasome formation, and migrasomes play a pivotal role in the invasiveness and angiogenesis of liver cancer cells, thereby facilitating HCC progression." (PMID 38840183, 2024). "Our study delves into altering CD151 expression levels to investigate the secretion of migrasome and the invasive properties of liver cancer." (PMID 38840183, 2024). "We explore the role of migrasome in HCC-related neovascularization and metastasis, ultimately revealing that elevated CD151 expression upregulates migrasome expression in liver cancer." (PMID 38840183, 2024).
liver cancer (continued). "It was also reported CD151 can form complexes by interacting with integrins α3β1 and α6β1, which thus affect the biological functions of the liver cancer cells." (PMID 34108040, 2021). "CD151 (Tspan24) was first identified as a promoter of metastasis; its expression is increased in liver cancer, compared to normal cells." (PMID 25033048, 2014). "TSPAN4 serves as a migrasome marker in liver cancer, correlating with CD151 expression." (PMID 40909272, 2025). "Our hypothesis posits that CD151 influences migrasome generation, thereby impacting vascular remodeling and neovascularization in liver cancer." (PMID 38840183, 2024). "Consequently, these findings reinforce the assertion that CD151 expression significantly influences both migrasome generation and the invasiveness of liver cancer cell lines." (PMID 38840183, 2024). "Some studies have reported that abnormal gene expression, such as that of CD151, CD44, CD44s, CK-19, MMP, OPN, KLF8, TGF-beta and HRP-3, is closely associated with the development and progression of liver cancer." (PMID 24324629, 2013). "Thus, CD151 evidently enhances angiogenesis in liver cancer." (PMID 38840183, 2024). "Our study revealed a significant correlation between CD151 expression and migrasome marker TSPAN4 in liver cancer, based on database analysis of clinical samples." (PMID 38840183, 2024). "Migration bodies, generated by highly CD151-expressing HCC cell lines, exhibit a signal localisation effect on neighbouring liver cancer cells, attracting and facilitating their engulfment." (PMID 38840183, 2024). "To investigate the correlation between CD151 and migrasome marker TSPAN4 in liver cancer, we conducted database analysis using clinical data from HCC patients." (PMID 38840183, 2024). "For example, Sp1 was found to affect the chromatin accessibility of CD151 and P2X7 receptor promoters in liver cancer cells 34 and neuroblastoma cells 35, respectively." (PMID 26763486, 2016). "We next examined the relationship between CD151, CD63, and TM4SF5 in human liver cancer tissues." (PMID 25033048, 2014).
Nephropathy (7 papers, 2013 to 2024). A nonspecific term referring to disease or damage of the kidneys. "The FVB/N strain, widely used in renal disease research, is highly susceptible to nephropathy in several renal disease models, including HIV-associated nephropathy, 75% nephrectomy, and CD151 knockout mice." (PMID 38674390, 2024). "A defect in the CD151 protein determines theclinical manifestations in individuals with CD151-associatedEBS, including nephropathy with proteinuria." (PMID 36923479, 2023). "Here, we outline the clinical presentation of a young girl with kidney disease associated with novel truncating variant in the CD151 gene." (PMID 35278129, 2022). "Homozygous mutations in CD151 gene encoding tetraspanin CD151 were reported in patients with EB simplex and nephropathy." (PMID 34123558, 2021). "Similarly, since CD151 is important for proper insertion of integrin α3β1, mutations in the gene CD151 cause a similar syndromic disease of nephropathy, pretibial epidermolysis bullosa and deafness." (PMID 32708597, 2020). "We aimed to better understand the relevance of CD151 in human kidney disease." (PMID 35278129, 2022).